ZNF28 (zinc finger protein 28)
Description:
May be involved in transcriptional regulation.
Synonyms: KOX24; DKFZp781D0275
Tractability: PROTAC: UniProt records ubiquitination sites on it; ubiquitination databases record sites on it.
Gene: Protein-coding gene on chromosome 19 (52,797,408 to 52,857,600, reverse strand). Ensembl gene ENSG00000198538.
Subcellular location: Nucleus
Pathways (Reactome):
Gene expression (Transcription): Generic Transcription Pathway; Regulation of endogenous retroelements by KRAB-ZFP proteins
Gene Ontology:
Molecular function: DNA-binding transcription factor activity, RNA polymerase II-specific; RNA polymerase II cis-regulatory region sequence-specific DNA binding; sequence-specific double-stranded DNA binding
Biological process: regulation of transcription by RNA polymerase II; regulation of DNA-templated transcription
Cellular component: nucleus
Genetic constraint (gnomAD): Loss-of-function variants: 1 observed, 2.14 expected, observed/expected ratio (o/e) 0.47, 90% interval 0.16 to 1.71. That is too few expected variants to judge how well the gene tolerates losing a copy. Missense variants: 831 observed, 829.37 expected, observed/expected ratio (o/e) 1, 90% interval 0.95 to 1.06. Synonymous variants: 266 observed, 275.79 expected, observed/expected ratio (o/e) 0.96, 90% interval 0.87 to 1.07.
Homologues: Orthologues: chimpanzee ZNF28 (96% identical), macaque ZNF28 (91% identical). Paralogues in human: ZNF658 (44% identical), ZNF600 (44% identical), ZNF33B (43% identical), ZNF726 (43% identical), ZNF841 (43% identical), ZNF595 (42% identical), ZNF724 (42% identical), ZNF836 (42% identical), ZNF708 (42% identical), ZNF534 (42% identical), ZNF728 (41% identical), ZNF254 (41% identical), and 164 more.
Diseases named in the same sentence as ZNF28 in open-access papers:
ZNF28 is named in the same sentence as 3 diseases in open-access papers, as found by Europe PMC text mining. Sharing a sentence is not in itself a finding about the gene and the disease. The quoted sentences say what the papers report.
lung adenocarcinoma (1 paper, 2019). A carcinoma that arises from the lung and is characterized by the presence of malignant glandular epithelial cells. "In lung adenocarcinoma of current smokers, genome-wide significant CpGs annotated to multiple small nucleolar RNA genes, ribosomal subunit genes (RSPs), myosin immunoglobulin (MYO1G), and zinc finger protein 28 (ZFP28)." (PMID 30872662, 2019).
psychiatric disorder (1 paper, 2023). A disorder characterized by behavioral and/or psychological abnormalities, often accompanied by physical symptoms. "ZNF28, on the other hand, was not previously associated with psychiatric disorders." (PMID 36253440, 2023).
ZNF28 also shares sentences with these, for which no sentence is quoted: non-small cell lung carcinoma (1 paper).